LIAS (lipoic acid synthetase)
Diseases named in the same sentence as LIAS in open-access papers (continued):
Sharing a sentence is not in itself a finding about the gene and the disease.
retinoblastoma (1 paper, 2022). A malignant tumor that originates in the nuclear layer of the retina. "The expression levels of LIAS in retinoblastoma (RB) were positively associated with angiogenesis and differentiation." (PMID 35982953, 2022).
steatosis (1 paper, 2024). Increased lipid within the cytoplasm of cells. "FDX1 also acts as a key regulator of steatosis by directly binding to LIAS, thereby exerting a lethal metabolic effect on cancer cells." (PMID 39360273, 2024).
uveal melanoma (1 paper, 2022). A melanoma derived from melanocytes of the uveal tract. "Furthermore, LIAS expression in uveal melanoma (UM) had a negative relationship with DNA damage, DNA repair, and apoptosis." (PMID 35982953, 2022).
tumor (44 papers, 2022 to 2025). "Surprisingly, IDH2R140Q mutation changed the expression patterns of cupropotosis-associated genes, including FDX1, LIAS, LIPT1, DLD, DLAT, and PDHA1, which indicated that the sensitivity of tumor cells to cuproptosis depends on the types of genetic mutations." (PMID 40384935, 2025). "Our findings suggest that lnc-CNNM3-DT functions as a protective factor in CC by inhibiting tumor progression through downregulation of LIAS expression and reduction of intracellular copper levels." (PMID 40265013, 2025). "Meanwhile, a large majority of cuproptosis-associated genes including FDX1, LIAS, DLD, DLAT, PDHA1, and GLS, were significantly associated with the tumor microenvironment (immune, stromal, and estimate scores) (p < 0.05)." (PMID 36105090, 2022). "In the GPL570 dataset, upregulation of LIPT1, FDX1, LIAS, DLAT, DLD, and PDHB was noted in tumor samples, while MTF1 was downregulated." (PMID 40410601, 2025). "Firstly, Western blot analysis revealed that compared to the Vector+PBS + PBS group, the RPS27-RPS24 + PBS + PBS group of mice showed a significant increase in the expression levels of RPS27-RPS24, GLS, FDX1, LIAS, and Lipoy-DLAT proteins in tumor tissues." (PMID 40280903, 2025). "When dataset was expanded with GTEx data, a similar pattern was observed for most genes, although LIAS, PDHA1, and PDHB showed downregulation in tumor tissues." (PMID 40410601, 2025). "Specifically, genes such as LIPT1, ATP7A, LIAS, DBT, and PDHB were found to be significantly downregulated in the tumor tissue." (PMID 38898987, 2024). "Au@MSN-Cu/PEG/DSF decreases the expression of DLAT, LIAS (Lipoic acid synthase), NPL4 and, in combination with photothermal therapy, effectively kills tumor cells and inhibits tumor growth." (PMID 38693584, 2024). "The methylation levels of LIAS, PDHB, and LIPT1 in the PDAC tumor tissues were significantly different from those in the normal tissues (FDR < 0.05)." (PMID 36826087, 2023). "Of note, seven out of ten pivotal CRGs, which were identified in Science article, showed significantly altered expression patterns, with CDKN2A exhibited higher and DLAT, DLD, FDX1, LIAS, MTF1, PDHB exhibited lower expression in tumor tissues (P<0.05)." (PMID 37384293, 2023). "The expression of COX11, COX17, LIAS, CDKN2A and AOC3 was significantly higher in tumor tissues than in normal tissues." (PMID 38078879, 2023). "By modulating different substance metabolism,FDX1,LIAS and DLAT, exert impact on tumor cell proliferation, migration, angiogenesis, immune arrest.Specifically,FDX1regulates steroid synthesis." (PMID 36925927, 2023). "The PDAC patients with higher expression levels of PDHA1, LIPT1, LIAS, and DLD, or lower expression levels of DLAT, in their tumor tissues had a better prognosis than their counterparts (p < 0.05)." (PMID 36826087, 2023). "ATP7A expression was significantly higher in tumor tissues than in paraneoplastic tissues, while FDX1, DBT, and LIAS expression was significantly lower than in paraneoplastic tissues (P<0.05)." (PMID 36568224, 2022). "The results showed that, in tumor samples, ATP7B, PDHA1, and SLC31A1 were significantly upregulated compared with normal tissues, whereas ATP7A, DLST, GCSH, LIAS, and LIPT1 were significantly downregulated." (PMID 36567939, 2022). "This called for more practical testing, so in the Taizhou cohort, we performed qRT-PCR experiments on 127 tumor tissues and their corresponding normal samples to obtain the expression of genes (FDX1, LIAS, PDHB, and MTF1)." (PMID 36212447, 2022). "Of the six cuprotosis-related genes, we found that FDX1, LIAS, DLAT, MTF1, and GLS were differentially expressed between tumor and normal tissue and were upregulated in normal tissue." (PMID 36247012, 2022). "Among them, 7 genes (DLAT, DLD, GCSH, LIAS, LIPT1, PDHA1, and PDHB) were upmodulated, whereas 3 genes (ATP7B, FDX1, and SLC31A1) were downmodulated in the tumor group in contrast with the normal group (p < 0.05)." (PMID 36046242, 2022).
tumor (continued). "A heatmap showed that the levels of expression of ATP7B, DLAT, DLD, LIAS, and SLC31A1 were upregulated and the levels of expression of DBT, FDX1, and PDHB downregulated in tumor samples." (PMID 36092880, 2022). "Of the six cuprotosis-related genes included in the signature, we found FDX1, LIAS, DLAT, MTF1, and GLS to be differentially expressed between tumor and normal tissues at the protein level." (PMID 36247012, 2022). "We found that LIAS and CDKN2A were significantly upregulated in tumor samples, and FDX1, DLD, DLAT, PDHA1, PDHB, MTF1, and GLS were significantly downregulated in tumor samples." (PMID 36531222, 2022). "Subsequently, we detected the expression of these CRGs in tumor and normal samples and found that 6 genes, FDX1, LIAS, DLD, DLAT, PDHB and MTF1, were significantly downregulated in tumors, while 2 genes, GLS and CDKN2A, were significantly upregulated." (PMID 36246586, 2022). "The expression of MTF1, NLRP3, and SLC31A1 was positively related with ImmuneScore, StromalScore, and ESTIMATEScore in almost all types of tumor, whereas ATP7B, DLAT, DLD, LIAS, PDHA1, and PDHB were significantly negatively correlated with the scores." (PMID 36387247, 2022). "Furthermore, the Cu+ concentration in tumor cells, generated by the reaction of Cu2+ with GSH, significantly increased, thus inhibiting the expressions of FDX1 and LIAS, triggering DLAT aggregation, and inducing cuproptosis in return." (PMID 38582500, 2024). "We found that five cuprotosis molecules, DLAT, PDHA1, FDX1, GLS and CDKN2A, were significantly different between paired tumour and adjacent non-tumour samples from the TCGA-STAD cohort, and LIAS, DLD, DLAT and MTF1 were significantly different among the four pathologic T categories 1–4." (PMID 36895378, 2023). "The results revealed that LIAS, DLAT, PDHA1, and CDKN2A were significantly upregulated in LUAD tumors compared to normal tissues, while ATP7B, SLC31A1, FDX1, MTF1, and GLS were significantly downregulated in tumor tissues." (PMID 36983664, 2023). "FDX1, LIAS, LIPTQ, SLC31A1, and PDHB showed no mutation in LUAD tumor tissues." (PMID 36983664, 2023). "LIAS may affect high oxidative phosphorylation cancer by regulating mitochondrial energy metabolism.LIAS may have an effect on tumor proliferation and invasion by regulating HIF-1.The expression of LIAS is correlated with the infiltration of immune cells,which may lead tumor immune escape." (PMID 36925927, 2023). "Moreover, differential CDKN2A and LIAS methylation levels were noted in the tumor and adjacent nontumor tissues." (PMID 36092958, 2022). "Levels of expression of the ATP7B, DLAT, and LIAS proteins were higher, whereas the levels of expression of DBT and PDHB were lower, in tumor samples than in non-tumorous kidney tissue, in accordance with the results of differential mRNA analysis." (PMID 36092880, 2022).
cancer (28 papers, 2016 to 2025). A tumor composed of atypical neoplastic, often pleomorphic cells that invade other tissues. "Among these cancers, the cuproptosis key genes, LIAS, FDX1, and DLAT tended to show copy number deletion, while DLD tended to show copy number amplification." (PMID 38573998, 2024). "LIAS expression was up-regulated in CCA, HCC, LUAD, DLBC, THYM, and LUSC, on the contrary, LIAS expression was down-regulated in the majority of cancers, such as BRCA, COAD, ccRCC, KIRP, PRAD, READ, THCA and UCEC." (PMID 39482784, 2024). "Inhibitors of FDX1 or LIAS have been studied for their anti-cancer activity, and have shown promising results in preclinical studies." (PMID 37564178, 2023). "As to the genes of copper death, ATP7A is positively related to 29 cancers, while LIAS is negatively related to 13 tumors." (PMID 37671947, 2023). "Lipoic acid synthetase (LIAS) has been demonstrated to play a crucial role in the progression of cancer." (PMID 35982953, 2022). "On the contrary, KIRCs were found to potentially have a lower copper cell death in cancer tissue because their anti-cuproptosis gene ATP7B was upregulated with pro-copper metabolism-related cell death genes SLC31A1, FDX1, DLAT, and LIAS downregulated in cancer tissues." (PMID 36276096, 2022). "Furthermore, we compared the differential expressions of cuproptosis-related genes between OSCC tissues and para-cancer tissues and found that four genes (LIAS, PDHB, GLS, and CDKN2A) were differentially expressed." (PMID 35875097, 2022). "Therefore, lnc-CNNM3-DT may further inhibit the metabolic activity and antioxidant capacity of CC cells by downregulating LIAS expression, thereby enhancing its anti-cancer effects." (PMID 40265013, 2025). "LIAS may have a potentially critical role in regulating biological functions in cancer." (PMID 40265013, 2025). "Moreover, LIAS expression had a negative relationship with cancer-associated fibroblast in COAD, KIRC, SARC, TGCT, and THCA." (PMID 35982953, 2022). "Thus, we investigated the methylation levels of LIAS in TCGA pan-cancers by the UALCAN database." (PMID 35982953, 2022). "Moreover, the LIAS expression was upregulated in some cancers, such as CHOL, LIHC, LUAD, and LUSC." (PMID 35982953, 2022). "Indeed, several somatic mutations in LIAS or OGDH have been collated (Catalogue of Somatic Mutations in Cancer [COSMIC] database), and a number of the LIAS mutations are similar to the known homozygous mutations, which tend to occur around the Fe-S cluster coordination sites." (PMID 27923773, 2016). "In this pan-cancer analysis, we systematically profiled the expression and prognostic value of eight well-characterized cuproptosis-related genes—FDX1, LIAS, LIPT1, DLD, DLAT, PDHA1, PDHB, and SLC31A1—across 34 cancer types." (PMID 40601654, 2025). "As three key genes in cuproptosis, FDX1, LIAS, and DLAT, are expected to be the targets in cancer therapy." (PMID 36925927, 2023). "In the differential expression analysis of oral squamous cell carcinoma and adjacent tissues, LIAS and PDHB were inhibited in cancer tissues, while GLS and CDKN2A were promoted in cancer tissues." (PMID 36600313, 2023). "The differential expression analyses of OSCC tissues and para-cancer tissues demonstrated that LIAS and PDHB were suppressed in cancer tissues, but GLS and CDKN2A were accelerated." (PMID 35875097, 2022). "The expression of DLAT, LIAS, and ATP7B was negatively correlated with the methylation in most of the cancer types." (PMID 36276096, 2022). "LIAS and PDHB were cuproptosis promoters with low expression in cancer tissues, while GLS and CDKN2A were cuproptosis suppressors with high expression in cancer tissues." (PMID 35875097, 2022). "Furthermore, a major enzyme in lipoate metabolism, lipoic acid synthetase (LIAS), has been suggested as a novel biomarker for prognosis and immune response in various cancers." (PMID 41440999, 2025).
cancer (continued). "Although we found that AURKA, as a ferroptosis-related gene, may be associated with cuproptosis-related genes such as DBT, DLST, LIAS, and PDHA1, how they interact with each other to influence cancer development needs to be investigated in depth." (PMID 38673957, 2024). "Germline mutations in LIAS, LIPT2 and LIPT1 result in impaired PDHc and OGDHc activity, but ABHD11 loss did not significantly alter DLAT lipoylation in several cancer lines." (PMID 32792488, 2020). "Specifically, upon entering the cancer cells either through interactions between Zn and ZFPs directing them toward Mito, ZCE disrupted the preparation of Fe-S protein in mitochondrial electron transport chain (ETC) through down-regulating the expression of FDX2/LIAS and ZIP7 to activate Znproptosis." (PMID 40225560, 2025). "The expression levels of LIAS had a positive correlation with the expression levels of CTD-2366F13.1 (R = 0.47, p < 0.001), RAD17 (R = 0.48, p < 0.001), OCIAD1 (R = 0.49, p < 0.001), PACRGL (R = 0.49, p < 0.001), MRPS27 (R = 0.49, p < 0.001), and THAP9 (R = 0.49, p < 0.001) in pan-cancer." (PMID 35982953, 2022). "Moreover, the promoter methylation levels of LIAS in KIRC were higher than those in the normal group, whereas there existed no significant changes in LIAS methylation levels in other cancers." (PMID 35982953, 2022). "For example, the expression of DLAT, LIAS, and ATP7B was negatively correlated with the methylation in most of the cancer types, while the expression of SLC31A and FDX1 was not remarkably correlated with the methylation in most of the cancer types." (PMID 36276096, 2022). "Results showed that the cancer–noncancer protein expression patterns of ATP7B, SLC31A1, DLAT, and LIAS were mostly consistent with the patterns at the mRNA level but that of FDX1 was not." (PMID 36276096, 2022).
mitochondrial disease (3 papers, 2020 to 2022). "Some studies have shown that three human mitochondrial diseases that directly affect lipoic acid metabolism result from heterozygous missense and nonsense mutations in LIAS, LIPT1, and LIPT2 genes." (PMID 35619696, 2022). "A second group of mitochondrial diseases is defined by mutations in lipoic acid synthase, Lip5/LIAS (S. cerevisiae/humans), and protein lipolylation defects." (PMID 33487163, 2021). "Three human mitochondrial diseases that directly affect lipoic acid metabolism result from heterozygous missense and nonsense mutations in the LIAS, LIPT1, and LIPT2 genes." (PMID 32508887, 2020).
infection (2 papers, 2021 to 2025). The state of being infected such as from the introduction of a foreign agent such as serum, vaccine, antigenic substance or organism. "Our findings established liaS as a pivotal genetic determinant in the pathogenesis of caries in dual-species infections." (PMID 40822408, 2025). "In contrast, liaS– infections significantly reduced the incidence of Dx lesions (P < 0.05) across both single-species and dual-species infections." (PMID 40822408, 2025). "In vivo, liaS deletion attenuated the cariogenicity of S. mutans, even in dual-species infections, thus phenocopying the non-pathogenic biofilm behavior of C. albicans alone." (PMID 40822408, 2025). "Notably, the liaS– and C. albicans combined infection displayed caries patterns that were phenotypically aligned with those of C. albicans single infection, which demonstrated minimal cariogenic activity." (PMID 40822408, 2025). "Wild type E. faecalis OG1RF, an ireK in-frame deletion mutant and transposon (Tn) insertion mutants of liaR, liaS, croR, and croS all display similar growth kinetics in the absence of phage VPE25 infection." (PMID 33411815, 2021).
digestive diseases (1 paper, 2022). "The four overlapping genes, including LIAS, DLAT, DBT, and PDHA1, were dysregulated expressed in the interaction between the four digestive diseases using the Venn diagram." (PMID 36405733, 2022).
inflammation (1 paper, 2024). Aberrant reaction of the microcirculation characterized by movement of fluid and leukocytes from the blood into extravascular tissues. "Additionally, upregulated cuproptosis-related genes (LIAS and PDHB) were found to be positively associated with the occurrence of pulmonary inflammation in a septic mouse model." (PMID 39427197, 2024).
metabolic disorders (1 paper, 2025). "In previous studies, it was found that deletion of FDX1 and LIAS conferred resistance to copper-induced cell death, but it has also been shown that defects in neonatal LIAS are associated with severe metabolic disorders." (PMID 40337173, 2025).
LIAS also shares sentences with these, for which no sentence is quoted: lung adenocarcinoma (3 papers); colorectal cancer (2); Crohn disease (2); diabetes (2); diabetic kidney disease (2); hepatocellular carcinoma (2); rectal adenocarcinoma (2); thyroid cancer (2); ulcerative colitis (2); Alzheimer disease (1); atherosclerosis (1); bacterial infections (1); bladder cancer (1); bone cancer (1); breast invasive carcinoma (1); cardiomyopathy (1); colon adenocarcinoma (1); convulsion (1); encephalomyopathy (1); Epileptic encephalopathy (1); eye cancer (1); Familial adenomatous polyposis (1); Friedreich ataxia (1); gallstones (1); gastrointestinal tumors (1); glioblastoma (1); head and neck tumor (1); hyperglycaemia (1); Hypertension (1); hypertrophic cardiomyopathy (1).
A further 19 diseases each share a sentence with LIAS in 1 paper.